LIPT1 (lipoyltransferase 1)
Diseases named in the same sentence as LIPT1 in open-access papers (continued):
Sharing a sentence is not in itself a finding about the gene and the disease.
mitochondrial disease (3 papers, 2020 to 2025). "Moreover, this connection has been also demonstrated in rare mitochondrial diseases induced by mutation in lipoyltransferase 1 (LIPT1) gene." (PMID 40003902, 2025). "Some studies have shown that three human mitochondrial diseases that directly affect lipoic acid metabolism result from heterozygous missense and nonsense mutations in LIAS, LIPT1, and LIPT2 genes." (PMID 35619696, 2022). "Three human mitochondrial diseases that directly affect lipoic acid metabolism result from heterozygous missense and nonsense mutations in the LIAS, LIPT1, and LIPT2 genes." (PMID 32508887, 2020).
LIPT1 also shares sentences with these, for which no sentence is quoted: lactic acidosis (4 papers); thyroid cancer (3); cardiomyopathy (2); clear cell renal cell carcinoma (2); developmental delay (2); glioblastoma (2); kidney cancer (2); lymphoid neoplasm (2); periodontitis (2); rheumatoid arthritis (2); skin cutaneous melanoma (2); bone cancer (1); brain cancer (1); breast invasive carcinoma (1); cervical squamous cell carcinoma (1); colon adenocarcinoma (1); convulsion (1); coronary heart disease (1); depression (1); diabetes (1); dihydrolipoamide dehydrogenase deficiency (1); Encephalopathy (1); endocervical adenocarcinoma (1); esophageal carcinoma (1); eye cancer (1); gastroenteritis (1); gastrointestinal tumors (1); genetic disorders (1); head and neck tumor (1); Hyperglycemia (1).
A further 24 diseases each share a sentence with LIPT1 in 1 paper.